SDC1 (syndecan 1)
Diseases named in the same sentence as SDC1 in open-access papers (continued):
Sharing a sentence is not in itself a finding about the gene and the disease.
cancer (continued). "The role of SDC-1 as adhesion molecule in the cell surface preferentially to collagen I36,40, can be suppressed with the shedding of its extracellular domain, a mechanism well described in cancer cells, and mediated mainly by the matrix metalloproteinases (MMPs) 7 and 936,43,56." (PMID 30065348, 2018). "Upregulation of syndecan-1 has been described in some types of tumors, and it has been postulated that this aberrant expression may play a key role in promoting growth factor signaling in cancer cells." (PMID 29940912, 2018). "The reason why the molecular profile of the two different histological types of cancer, in spite of the same origin, shows an identical epithelial Sdc1 expression, but, for example, completely opposite E-cadherin expression, remains unclear and requires further studies." (PMID 30151336, 2018). "Therefore, Sdc1-dependent metastatic efficiency may be due to the stimulation of carcinoma cell proliferation by stromal cell-derived Sdc1." (PMID 29976229, 2018). "Sdc-1 interacts with insulin-like growth factor 1 receptor and integrins enabling angiogenesis and cell survival hence blocking of Sdc-1 via synstatin might result in new therapeutic approaches in cancer treatment." (PMID 28293067, 2017). "Upregulation of syndecan-1 has also been described in tumors other than those of the colon, and it has been postulated that this aberrant expression may play a key role in promoting growth factor signaling in cancer cells." (PMID 26482785, 2015). "In addition, soluble SDC1 can act as decoy receptor, and thus it may promote cancer progression by sequestering inhibitory molecules." (PMID 26293675, 2015). "Therefore, appropriately targeting SDC1 in selected cancers may guide precision therapeutic options." (PMID 26293675, 2015). "Finally, epithelial and/or stromal syndecan-1 expression is of prognostic value in many carcinomas." (PMID 18542065, 2008). "Cell surface proteins such as E-cadherin, N-cadherin, Syndecan-1 and cytoplasmic proteins such as Vimentin and α-SMA are involved in both embryo implantation and cancer." (PMID 39909974, 2025). "ACTG1, SDC1, FRS2, and WNT9B were commonly identified as genes contributing to the enrichment of the ‘Proteoglycans in Cancer’ pathway in both species." (PMID 41296454, 2025). "Cell surface heparan sulfate proteoglycans (HSPGs), namely, syndecan-1 (SDC1), SDC2, and SDC4, are involved in cancer progression, metastasis, and regulate extracellular vesicles (EVs) biogenesis, including the microvesicles (MVs)." (PMID 40940401, 2025). "Target prediction and functional annotation identified 59 overlapping genes, with the Proteoglycans in cancer pathways being conserved in both species, mediated by ACTG1, SDC1, FRS2, and WNT9B." (PMID 41296454, 2025). "While Indatuximab ravtansine is primarily studied in cancer contexts, our findings highlight its potential application in DFU treatment by targeting SDC1-mediated signaling pathways, particularly those involved in inflammation and wound-healing processes." (PMID 40722759, 2025). "Syndecan-1 (SDC1), a heparan sulfate proteoglycan, is part of the syndecan family and is crucial in the advancement of cancer." (PMID 38189813, 2024). "In contrast, the expression levels of TXNDC5, CD38, GAS6, FKBP2 and SDC1 were increased in the late stage of LUAD progression, indicating potential distinct roles in the occurrence and progression of the cancer." (PMID 37728413, 2023). "For example, the ofCS-modified proteoglycan such as ofCS-CD44, -CSPG4, and -SDC1 can present as free form, attached with CTC, or largely with cancer-derived exosomes in plasma." (PMID 36746966, 2023). "SDC1 has been known to play an important role in the invasion, migration and EMT in cancer cells by regulating ERK/Snail signaling." (PMID 37069585, 2023). "To quantitate the plasma ofCS/ofCSPGs, we optimized an ELISA using different capture/detection pairs (rVAR2/anti-CD44, -SDC1, and -CSPG4) in a case-control study with six cancer types." (PMID 36746966, 2023).
cancer (continued). "Using a biomarker discovery set consisting of 302 healthy controls and 165 malignant tumor patients, we found that the plasma ofCS-CD44, -SDC1, -CSPG4, and total ofCS in all types of cancer tested were significantly higher than that in healthy controls." (PMID 36746966, 2023). "Different molecules such as EGFR, PTEN, V-ATPase, syndecan 1 and galectin-3 play distinct roles in the metabolic regulation of RAS-mediated macropinocytosis in cancer." (PMID 37535087, 2023). "In particular, we found that SDC1 was a key receptor mediating COL1A1+ CAFs and cancer cells, and it was significantly upregulated in both cell types." (PMID 37021816, 2023). "Three ofCS modified glycoproteins (ofCS-CD44, SDC1, and CSPG4) detected across multiple cancer cells by rVAR2 were selected because of their important roles in cancer progression and metastasis." (PMID 36746966, 2023). "In Cluster 2 the EMT related genes, including Fn1, Vim and Sdc1, were significantly upregulated, suggesting that Cluster 2 underwent active EMT, one of the major features of cancer progression." (PMID 35941362, 2022). "For cytokines, CCL5 is highly expressed in CD8 + T cells, NK Cells, NKT Cells, CD4 + T Memory Cells, Plasma Cells, and Langerhans Cells and strongly interacts with SDC1 and SDC4 in Cancer Cells, affecting cancer progression, development, and the survival." (PMID 36401283, 2022). "YKL-40 can bind chitin, heparin, collagen, and hyaluronan, and it has been suggested to promote cancer through binding to the IL-13Rα2, RAGE, syndecan-1, and CD44v3 receptors on the surface of cancer cells." (PMID 35631632, 2022). "Here we outlined the remarkable features of HSPGs, such as GPC1, GPC4, GPC5, SDC1, SDC2, SDC3 and HSPG2, and some HSPG-related proteins like heparanase and SULF1/2, in cancer diagnosis." (PMID 34249755, 2021). "We found all expression-validated cancer and migration-related genes had at least one putative DRE(s) in their promoters, especially CYP1B1, ID1, and SDC1, which had 8, 5, and 6 putative DRE sites, respectively." (PMID 34955744, 2021). "CCL5 is another chemokine that we identified as positively associated with the immune response when bound to different receptors (SDC4, SDC1, and CXCR3 for 16, 15, and 13 cancer types, respectively)." (PMID 34430923, 2021). "Syndecan-1 (SDC1) is the major cell surface proteoglycan in epithelial cells and has been shown to regulate carcinoma progression and EMT." (PMID 34208075, 2021). "Syndecan-1, a coreceptor and cooperator with HGF and HER2, respectively, activates proliferative signals and improves cancer cell survival." (PMID 32825245, 2020). "Syndecan-1 (SDC1) is an HSPG that is overexpressed in both normal and malignant cells, contributing to the development of hematopoietic and carcinoma development." (PMID 32471161, 2020). "Thus, reduction of shedding syndecan-1 may be a novel therapeutic approach to treat cancer." (PMID 30135409, 2018). "First, we compared IL-34,CSF-1, CSF-1R, PTPRZ1, and SDC1 gene expression between human MCF7, SK-BR-3 and MDA-MB-231 cancer cells in comparison to human THP-1 macrophages." (PMID 29796177, 2018). "Syndecan (SDC) is a member of heparan sulfate proteoglycan (HSPG) family, where SDC-1 promote cancer cell proliferation and integrin-mediated binding for cell adhesion and migration." (PMID 29881724, 2018). "As Syndecan-1 is an important modulator of inflammation and the CSC phenotype in different experimental models and in cancer, it emerges as a candidate marker for IBC." (PMID 28270211, 2017). "Overexpression of syndecan-1, MUC-1, and the putative cancer stem cell markers CD15, CD24, CD44, and CD133 has been documented on CSF floating cancer cells of BC patients with LM." (PMID 28399903, 2017). "In myeloma cells it was shown that syndecan-1 is shed and the binding of VEGF through its heparan sulfate chains stimulated tumor angiogenesis further supporting cancer growth." (PMID 27809279, 2016).
cancer (continued). "Reduced Sdc1 and elevated HPSE have been commonly reported in malignant tumours, bacterial infections and chronic inflammatory diseases 13,22,23." (PMID 25702768, 2015). "Notably, only one pathway, Proteoglycans in cancer (p < 0.05), was conserved across both species, with ACTG1, SDC1, FRS2, and WNT9B identified as common genes participating in this pathway." (PMID 41296454, 2025). "Furthermore, saliently enhanced expression levels of MMP7 and SDC1, which correlated with extracellular matrix remodelling, in MUC1+ cancer cells within the chemotherapy cohort was discovered, further supported by the GSVA findings." (PMID 39422697, 2024). "Most importantly, ITGA6 and SDC1 were highly expressed in HeLa and OVSAHO cancer cells." (PMID 39271776, 2024). "Sortilin regulates glucose metabolism and is upregulated by androgen, which also induces glucose uptake, while androgen deprivation leads to overexpression of syndecan-1 and increases its interactions with LPL and αVβ3 integrin to facilitate lipid metabolism and cancer aggression." (PMID 37596305, 2023). "myCAFs may also express other matrix proteins including THBS1 (thrombospondin 1), THBS2, and TNC (tenascin C, a matrix protein), to communicate with immunocytes, smooth muscle cells, cancer cells, and plasma cells through CD44, integrin (α3β1), and SDC1." (PMID 35986392, 2022). "The highly expressed cytokine CCL5 in CD8 + T Cells, NK Cells, NKT Cells, CD4 + T Memory Cells, Plasma Cells, and Langerhans Cells work together with SDC1 and SDC4 in Cancer Cells to affect the occurrence, development, and mediation of cancer survival of cancer cells." (PMID 36401283, 2022). "In addition, macrophages and endothelial cells secreted large numbers of cytokines which interacted with SDC1, SDC4, and ITGB1 in cancer cells." (PMID 34745098, 2021). "It remains to be determined whether AP4 regulates the expression of SDC1 and PRPS2 and plays a role in disease progression via these two genes in these cancer types." (PMID 33567514, 2021). "While the mesenchymal signal in simulated bulk expression profiles predominantly reflects the presence of CAFs, our analysis also identifies specific ESGs (e.g. SNAI2, SDC1/4 and LAMC2) whose expression levels in the cancer cells are higher than or comparable to those in CAFs." (PMID 33972543, 2021). "Syndecan-1 (also known as SDC-1 or CD138) is a transmembrane proteoglycan that is expressed in many hematological and solid tumors and affects the prognosis of those cancers." (PMID 32983743, 2020). "Although, in vitro studies demonstrated that proliferation of cancer cells is stimulated by stromal syndecan-1, we failed to prove its negative effects in vivo, most likely due to the involvement of additional regulatory factors." (PMID 32388727, 2020). "Verifying the corresponding in vivo relationship between Sdc-1 and Foxp3 mRNA expression, we found a negative correlation in carcinoma tissue of IBC patients." (PMID 31145753, 2019). "The expression of SDC-1 changes from within the cancer cell to ectopically during EMT, indicating that available SDC-1 within a scaffold could be useful for investigating cell migration." (PMID 29881724, 2018). "Sdc1 expression in fibroblasts also leads to the production of ECM with an aligned fiber architecture that is permissive to the directionally persistent migration and invasion of carcinoma cells." (PMID 29976229, 2018). "Cell surface SDC1 is thought to promote cell adhesion to the ECM and reduce cancer cell migration." (PMID 29230082, 2017). "Relative to non-IBC, our data indicate a significantly higher expression of Syndecan-1 transcript levels (P < 0.01), and higher positive staining of Syndecan-1 protein in tissues of IBC (P < 0.01), and on carcinoma cells infiltrated into lymphatic vessels, a unique feature for IBC." (PMID 28270211, 2017).
cancer (continued). "Since normal epithelial cells do not express these integrins but in most carcinomas they are upregulated, the syndecan-1-coupled ternary receptor complex is present mostly in tumors." (PMID 26420915, 2015). "Although there are several reports showing an alteration of SDC1 in human cancers, none of them clearly explains the control mechanism or the effects of SDC1 expression." (PMID 24373193, 2013). "Moreover, elevated expression of PHLDA2 is related to poor prognoses in several types of cancer, and PHLDA2 could upregulate SDC1 expression, which contributes to cancer cell aggressiveness." (PMID 36061148, 2022). "Furthermore, their direct contact with cancer cells induced the production of syndecan-1 in normal fibroblasts that lacked syndecan-1 expression in monoculture." (PMID 32388727, 2020). "Moreover, there is a negative correlation between expression of Sdc-1 mRNA and IL-4, IL-17 and Foxp3 mRNA levels in carcinoma tissues of IBC and that correlation was reversed in non-IBC." (PMID 31145753, 2019). "Interestingly, qPCR revealed that there was a negative correlation between Syndecan-1 and each of IL-4, IL-17, and Foxp3 mRNA expression in carcinoma tissues of IBC and that the correlation was reversed in non-IBC." (PMID 31145753, 2019). "Sdc1-expressing stromal fibroblasts also produce an altered ECM that is characterized by parallel, aligned fibronectin and collagen fibers, which is permissive to carcinoma cell migration and invasion and thus has the potential to promote carcinoma spread and metastasis." (PMID 29976229, 2018). "In addition to extensively-documented changes in degree of immunocyte infiltration and levels of inflammatory cytokines in the course of cancer-promoting colonic inflammation, alterations in the expression of HSPG (in particular, decrease in Sdc1) were observed in both mouse and human studies." (PMID 28350804, 2017). "Interestingly, we found a higher expression of Notch-1 mRNA and a significant positive correlation between Notch-1 & -3 and Syndecan-1 mRNA levels in carcinoma tissues of triple negative IBC vs non-IBC." (PMID 28270211, 2017). "Therefore, we analyzed Syndecan-1 expression by qPCR or immunohistochemical staining in carcinoma tissues of triple negative IBC vs non-IBC patients." (PMID 28270211, 2017). "Interestingly, a significant positive correlation between Notch-1 and Syndecan-1 mRNA levels (r = 0.793, P = 0.001) and between Notch-3 and Syndecan-1 mRNA levels (r = 0.819, P = 0.001) did exist in carcinoma tissues of IBC." (PMID 28270211, 2017). "Interestingly, detectable SDC1 was also observed in the stroma of malignant tumors and not in the benign breast tissue." (PMID 27434331, 2016). "Studies have revealed a mechanism by which syndecan-1 and -4 ectodomains, may capture and induce autophosphorylation of the tyrosine kinase receptors HER2 and EGFR respectively, leading to integrin mediated carcinoma cell migration." (PMID 26869927, 2016). "Therefore, in spheroids composed only of cancer cells, the absence of stromal interactions could potentially reduce SDC1 expression." (PMID 41228316, 2025). "Therefore, we examined expression of IL-17, Foxp3, IL-4 and Sdc-1 transcript levels in carcinoma tissue of non-IBC and IBC patients and tested whether there is any correlation among them." (PMID 31145753, 2019). "We characterized expression of Syndecan-1 and the CSC marker CD44, Notch-1 & -3 and EGFR in carcinoma tissues of triple negative IBC (n = 13) and non-IBC (n = 17) patients using qPCR and immunohistochemistry." (PMID 28270211, 2017). "In this study, we examined the expression of Syndecan-1 and its correlation with the CSC marker CD44, Notch-1 & -3 and EGFR expression in carcinoma tissues of triple negative IBC and non-IBC patients." (PMID 28270211, 2017).
cancer (continued). "The use of the 3G10 antibody demonstrated the presence of syndecan-1 in the co-culture medium, whereas this proteoglycan was absent from the conditioned medium of MCF-7 cells and from the plasma from a woman who was not affected by cancer (data not shown)." (PMID 30922347, 2019). "Syndecans are often found to be dysregulated in many types of cancer and their overexpression have been detected in ER-negative breast cancer cells (HER2-positive and triple negative breast cancer) but not in ER-positive as Sdc-1 expression is suppressed by ER." (PMID 37190188, 2023). "While the small number of cancer samples did not allow assessment of statistical significance, several of the new markers identified through mRNA analysis also showed trends of increased protein expression in SQCCs relative to ADCs (CD71/TFRC, CD9, PDPN, CD138/SDC1, CD99)." (PMID 25551685, 2014).